HMOX1 (heme oxygenase 1)
Diseases named in the same sentence as HMOX1 in open-access papers (continued):
Sharing a sentence is not in itself a finding about the gene and the disease.
diabetes (continued). "Also, dissimilar expression of heme oxygenase-1 according to diabetes stage has been found, which indicates an increase in heme oxygenase-1 level in the early phases and a subsequent decrease in the late stages." (PMID 27936224, 2016). "The spinal cord reacts to diabetes by neuronal apoptosis, microglial activation, and astrocytosis, with a disturbance in neuronal and glial Nuclear factor erythroid 2-related factor/Heme oxygenase-1 (Nrf2/HO-1) and Nuclear factor kappa-light-chain-enhancer of activated B cells (NF-kB) signaling." (PMID 36968023, 2023). "Moreover, SOX2OT knockdown is neuroprotective in diabetes-related retinal neurodegeneration in vivo, playing an antioxidative role via regulation of nuclear factor erythroid 2 related factor 2/heme oxygenase-1 (NRF2/HO-1) signaling activity in vitro and in vivo." (PMID 29074557, 2017). "For instance, renal ischemia, commonly observed in diabetes, induces the overexpression of hypoxia-inducible factor (HIF), particularly heme oxygenase-1 (HO1)." (PMID 39279996, 2024). "Deficiencies in antioxidant defenses against ROS described in diabetes included antioxidant enzyme such as SOD1, PRDX1, Hmox1 and antioxidants, thioredoxin 1 (Txn1)." (PMID 37337262, 2023). "Salidroside protects against diabetes-induced cardiac dysfunction by modulating the mechanistic target of rapamycin (mTOR), AMPK, and AKT/heme oxygenase-1(HO-1) signaling pathways." (PMID 35281941, 2022). "NRF2 activates the transcription of a cohort of antioxidant genes, such as heme oxygenase-1 (Ho1) and NAD(P)H dehydrogenase quinone 1 (Nqo1), the proteins of which work as scavengers of diabetes-induced free radicals." (PMID 28698767, 2017). "Finally, although we were able to rule out associations between HMOX1 repeat length and incident conditions such as diabetes, we could not easily explore the association between an inducible stress response gene and relevant outcomes (e.g., infection outcomes) in a biobank analysis." (PMID 37414746, 2024). "Moreover, diabetes is a risk factor in both PCOS and UCEC, and HMOX1, RTN1, and KCNJ15 are considered diabetes-related genes." (PMID 37363398, 2023). "Diabetes induced an increase in the expression of monocyte chemoattractant protein-1 (MCP-1), the macrophage marker F4/80, nitrotyrosine, Nox2, heme oxygenase-1 (HO-1) and platelet derived growth factor (PDGF)." (PMID 35798762, 2022). "Resveratrol inhibits diabetes-related cardiac dysfunction and hypertrophy in multiple low doses of streptozotocin-induced diabetic mice by restoring NRF2 and its downstream antioxidative genes, such as SOD, heme oxygenase-1 (HO-1), and metallothionein (MT)." (PMID 34942962, 2021). "Furthermore, H3K9 hyperacetylation of multiple genes including HMOX1, IL-8, HMOX1, MMP10, Cox2 and TNFα has been detected in vascular cells and immunocytes in patients with diabetes." (PMID 33988232, 2021). "The expression of the transcription factor NF-E2-related factor 2 (Nrf2) in the nucleus and its target genes heme oxygenase-1 (HO-1) and NAD(P)H:quinone oxidoreductase 1 (NQO1) at the 20th and 24th weeks of diabetes was significantly increased in the db/db mice compared with the db/m mice." (PMID 32194828, 2020). "In further support of how our model may explain the link between excess iron and the onset of diabetes, several lines of evidence indicate that boosting heme oxygenase-1 (HO-1; also known as HMOX1) activity, which lowers heme levels, can alleviate diabetes." (PMID 28794014, 2017). "However, this study opens the gate to new researches about the role of HMOX1, TXNIP, and Nrf2 in obesity, diabetes, and worse metabolic traits." (PMID 27274779, 2016). "Heme oxygenase-1 (HO-1), a stress response protein, is cytoprotective, but its role in post myocardial infarction (MI) and diabetes is not fully characterized." (PMID 24658657, 2014).
diabetes (continued). "Furthermore, diabetes alters the expression of several genes involved in mitochondrial stress (including mitochondrial membrane pore protein VDAC1, aconitase 2 and heme oxygenase-1) and neuronal injury (such as tyrosine hydroxylase and synaptic protein synaptopodin)." (PMID 28492550, 2017). "Transgenic expression of heme oxygenase-1, which has crucial cytoprotective functions against oxidative stress and inflammation, can improve insulitis and spontaneous diabetes in NOD mice, and alloxan-induced diabetes is also reduced following overexpression of Cu/Zn SOD in β-cells." (PMID 21647409, 2011). "Moreover, western blot further confirmed total superoxide dismutase 1 (SOD1), heme oxygenase-1 (Hmox1) and glutamate cysteine ligase (GCLc) expression at protein level, supporting the hypothesis of PNS up-regulated antioxidants to ameliorate diabetes-induced oxidative stress." (PMID 37337262, 2023).
Sepsis (240 papers, 2009 to 2026). Sepsis is defined as life-threatening organ dysfunction caused by a dysregulated host response to infection. "In vivo studies have confirmed that RES can protect against acute lung injury in rats with sepsis by upregulating antioxidant cytokines such as heme oxygenase-1 (HO-1) and nuclear factor-2 associated factor (Nrf2)." (PMID 39563478, 2024). "The univariate model showed that lower HMOX1 DCt values, corresponding to higher mRNA expression, correlated with an increased risk of sepsis/septic shock development (odds ratio (O.R.)= 0.259, 95% C.I. = 0.125–0.534, and p < 0.0001)." (PMID 37367740, 2023). "In fact, numerous studies have consistently highlighted the significant role of ferroptosis in the development of sepsis-induced heart injury, and Ptgs2, Hmox1, and Slc7a11 are well-recognized ferroptosis-associated targets by academia." (PMID 37424906, 2023). "The HMOX1 promoter GT(n) polymorphism has been studied across a broad range of infections, with the most studies in malaria and sepsis." (PMID 35551540, 2022). "The HO-1 genetically deficient mice (Hmox1−/−) displayed a phenotype of sensitivity to polymicrobial sepsis, relative to wild-type mice." (PMID 34073678, 2021). "When challenged with the cecal ligation and puncture (CLP) method to induce polymicrobial sepsis, HO-1-deficient mice (Hmox1-/-) were more susceptible to the lethal effects of CLP relative to wild type mice." (PMID 33228260, 2020). "In particular, iNOS induction and subsequent NO production as well as heme oxygenase-1 (HO-1) induction and associated carbon monoxide (CO) production influence mitochondrial respiratory function, mitophagy, and biogenesis in sepsis." (PMID 31772705, 2019). "Decreased levels of haptoglobin, hemopexin, and heme oxygenase-1 occur in critical illness, including patients with sepsis and ARDS, and decreased levels have been associated with poor clinical outcomes." (PMID 26933497, 2015). "Another line of evidence comes from the finding in patients with severe sepsis, that a heme oxygenase 1 polymorphism is associated with outcome." (PMID 22800762, 2012). "Using the cecal ligation and puncture (CLP) technique to induce sepsis, HO-1-deficient mice (Hmox1−/−) suffered higher mortality rates compared with HO-1 sufficient mice." (PMID 22518295, 2012). "In addition to Ptgs2 as a recognized biomarker in sepsis-induced cardiac injury, Hmox1 and Slc7a11 were reported as ferroptosis-associated targets in sepsis cardiac dysfunction." (PMID 37424906, 2023). "Therefore, our study first demonstrated two novel ferroptosis-associated targets in sepsis-induced cardiac injury: Hmox1 and Slc7a11 through bioinformatic selection and laboratory measurement." (PMID 37424906, 2023). "Our results indicate that ICU admission values of HMOX1 gene expression could reveal patients at risk of developing sepsis and septic shock." (PMID 37367740, 2023). "This study reports Hmox1 and Slc7a11 as ferroptosis-associated targets in sepsis-induced cardiac injury, and both of them may become key therapeutic and diagnostic targets for this complication in the future." (PMID 37424906, 2023). "ROC curve analysis in combination with multivariate regression analysis indicated that HMOX1 levels could be used as an independent prognostic factor for patients with a higher risk of developing sepsis and septic shock." (PMID 37367740, 2023). "Hepatic injury caused by sepsis was also protected in mouse models via HMOX1-induced autophagy." (PMID 32899231, 2020). "Altogether 653 patients with sepsis were successfully genotyped for HMOX1-promoter polymorphism." (PMID 31120979, 2019). "It has been hypothesized that quercetin and kaempferol, the core components of Sini Decoction, may modulate HMOX1 expression (a co-expressed gene in Sini Decoction) through associated signaling pathways to target CX3CR1 (a key gene influencing sepsis prognosis) in patients." (PMID 39495969, 2024).
Sepsis (continued). "By degrading pro-inflammatory heme and releasing anti-inflammatory molecules such as carbon monoxide, HMOX1 fine-tunes the acute inflammatory response with consequences for disorders of hyperinflammation such as sepsis." (PMID 38585264, 2024). "The activity of heme oxygenase in macrophages is also critical for controlling infection in sepsis, as mice with a myeloid-specific deletion of Hmox1 had higher bacterial burden and decreased survival in a model of E. coli peritonitis." (PMID 38585264, 2024). "In addition, free heme is a well-known inducer of heme oxygenase-1 (HO-1), particularly in monocyte/macrophage cells, which has been implicated as a key mediator of inflammatory cell and tissue injury, as validated in preclinical models of acute lung injury and sepsis." (PMID 38562925, 2024). "While Ptgs2 has been previously reported to be involved in the regulation of septic cardiomyopathy, this study is the first to demonstrate that downregulation of Hmox1 and Slc7a11 can alleviate ferroptosis in sepsis-induced cardiac injury." (PMID 37424906, 2023). "The fold change of Ptgs2, Hmox1, and Slc7a11 in sepsis-induced heart injury increased in 24 h and decreased in 48 and 72 h, which exhibited the same time trend as found previously." (PMID 37424906, 2023). "For the sake of comprehensiveness, GSE215955 and GSE53007 were used to validate the expression patterns of Hmox1 and Slc7a11, revealing that Hmox1 and Slc7a11 also had high expression in the sepsis group." (PMID 37424906, 2023). "The results showed that Hmox1 and Slc7a11 expressed highly in the sepsis group than in the control group." (PMID 37424906, 2023). "As far as we are aware, this is the first report to assign to HMOX1 expression a possible prognostic role for sepsis development." (PMID 37367740, 2023). "Recent studies showed that NOX4 was characterized in the cardiovascular system, HMOX1 can be induced by sepsis, and POR was selected as the central gene of SIC." (PMID 37035738, 2023). "Overall, our results indicate that HMOX1 mRNA levels have the potential to be a valuable predictive factor for the prognosis of sepsis and septic shock in ICU patients." (PMID 37367740, 2023). "In order to further investigate the role of Ptgs2, Hmox1, and Slc7a11 in sepsis-induced cardiac injury, we first investigated their expression levels in each group." (PMID 37424906, 2023). "Except for enzymes contributing to metabolic pathways, under hypoxia, HIFs regulate several genes with central roles in sepsis, including heme oxygenase-1 (HMOX1), erythropoietin (EPO), and the vascular endothelial growth factor (VEGFA)." (PMID 37367740, 2023). "H2 treatment, for instance, upregulated heat shock protein 32 (HO-1; heme oxygenase-1) in cardiac tissues, scavenging ROS and preventing sepsis-related damage to multiple organs in a HO-1/Nrf2 dependent pathway." (PMID 37509530, 2023). "Activation of mitochondrial biogenesis via Nrf2-dependent and independent induction of heme oxygenase-1 have been shown to be critical in survival in sepsis." (PMID 36978809, 2023). "Meanwhile, two novel ferroptosis-related targets were also selected in sepsis-induced cardiac injury: Hmox1 and Slc7a11." (PMID 37424906, 2023). "Three studies have examined the association between HMOX1 promoter repeats and outcomes in people living with HIV (PLWH), with quite differing results to that in sepsis and malaria." (PMID 35551540, 2022). "An important issue in sepsis is that the liver produces a large amount of carbon monoxide (CO) by oxidation of heme via the heme oxygenase-1 (HO-1) pathway." (PMID 35208760, 2022). "We also used a mouse model of sepsis-induced liver failure, and confirmed through qRT-PCR detection that ferroptosis-related genes Hmox1, Slc3a2, Jun and Zfp36 were significantly correlated with sepsis-induced liver failure." (PMID 35923893, 2022).
Sepsis (continued). "Disulfide HMGB1 inhibited the release of inflammatory cytokines in sepsis by binding to haptoglobin to induce heme oxygenase-1 (HO-1) and IL-10 production in a CD163+ dependent manner." (PMID 35250993, 2022). "Multiple studies based on model organisms have identified that the presence HMOX1 is critical to defend against certain infections, with some data supporting experimental upregulation of this enzyme being protective in animal sepsis and malaria models." (PMID 35551540, 2022). "The AUROC for the diagnosis of sepsis for HMOX1 and TLR4 ranged from 0.77 to 0.81, while the AUROC of MAPK14 reached 0.935 and 0.941 in the training and validation sets." (PMID 35844488, 2022). "For example, in myocardial tissues, H2 treatment scavenged ROS by upregulating the heme oxygenase-1 (HO-1, known as heat shock protein 32) to protect sepsis-related multiple organ injury in HO-1/Nrf2 dependent manner." (PMID 34987419, 2021). "The enhanced inflammation associated with sepsis was also attributed to increased levels of high-mobility group box-1 protein (HMGB1), which was augmented by Hmox1 deficiency, and ablated by pharmacological upregulation of HO-1 or application of CO." (PMID 33671004, 2021). "An in vivo experiment in sepsis-induced mice showed the dose-dependent action of mangiferin upregulated the action of HO-1 (heme oxygenase-1) and mediated the inflammation." (PMID 34646882, 2021). "In a nutshell we can say that HMOX1 plays a protective role against polymicrobial sepsis, acute inflammation response and thrombosis that are seen in critical SARS-CoV-2 patients." (PMID 32899231, 2020). "An in vivo study report demonstrated that hemin, which is an inducer of HMOX1, decreases IL1b and IL-18 secretion, and protects from sepsis-induced acute lung injury by inhibiting the excessive inflammatory response." (PMID 32899231, 2020). "An additional study demonstrated in vivo that HMOX1/CO plays a critical role in inhibiting LPS-mediated sepsis and pro-inflammatory cytokine production." (PMID 32899231, 2020). "Here, we focus on the role of the human HMOX1 protein, which has an important anti-inflammatory role in attenuating serious conditions like thrombosis, sepsis, tissue damage and fibrinogenesis, all of which are associated with SARS-CoV-2 infections." (PMID 32899231, 2020). "The pharmacological application of CORMs enhanced bacterial phagocytosis in vivo and rescued Hmox1-/- mice from sepsis-induced mortality." (PMID 33228260, 2020). "Sepsis and lipopolysaccharide (LPS)-induced autophagy via heme oxygenase-1 (HO-1) signaling also protects hepatocytes from death." (PMID 30642133, 2019). "In conclusion, the current study demonstrated that inhibition of miR-31 exerted positive effects on intestinal barrier dysfunction in sepsis, and HMOX1 was the target gene of miR-31." (PMID 30340459, 2018). "Herein, we evaluate the effect of microRNA-31 (miR-31) on intestinal barrier dysfunction through NF-κB/HIF-1α pathway by targeting HMOX1 in rats with sepsis." (PMID 30340459, 2018). "Overall, the current study found that inhibition of miR-31 protects against intestinal barrier dysfunction through suppression of the NF-κB/HIF-1α pathway by targeting HMOX1 in rats with sepsis." (PMID 30340459, 2018). "Thereby, the current study aims to investigate the effect of miR-31 on intestinal barrier dysfunction through the NF-κB/HIF-1α pathway by targeting HMOX1 in sepsis." (PMID 30340459, 2018). "Heme oxygenase-1 (HO-1) provides a protective mechanism by limiting oxidative stress-induced tissue damage during inflammation and sepsis." (PMID 26300888, 2015). "Erythrophagocytic macrophages have been shown to express heme-oxygenase 1 (HO-1) in human sepsis cases, and inhibit pro-inflammatory cytokine production in cultured mouse bone marrow cells (Slc11a1/Nramp1+/+), thereby suggesting an anti-inflammatory role." (PMID 20195482, 2010).